GFAP (glial fibrillary acidic protein)
Diseases named in the same sentence as GFAP in open-access papers (continued):
Sharing a sentence is not in itself a finding about the gene and the disease.
depression (continued). "In patients with MTLE, there was an increase in GFAP within the hippocampus among those with a history of interictal psychosis compared to those with no psychiatric history or a history of major depression." (PMID 40177583, 2025). "Day-of-injury GFAP did not have a relationship to incident depression or SI in the first year post-injury amongst patients with evidence of acute intracranial trauma at presentation (i.e. CT+patients)." (PMID 40190352, 2025). "Subgroup analyses revealed lower GFAP levels in patients with negative presenting head CT scans who met criteria for depression in the first year post-injury, regardless of pre-injury risk factors." (PMID 40190352, 2025). "There were positive correlations between plasma ITIH4 levels and 24-item Hamilton Depression Scale (HAMD-24) scores and plasma glial fibrillary acidic protein (GFAP) levels in MDD patients, however, plasma ITIH4 levels were significantly correlated with age just in adult MDD patients." (PMID 39323962, 2024). "The patient cohort was small, and not all NMOSD patients had their serum GFAP and NfL levels evaluated, or their anxiety and depression symptoms measured." (PMID 37324490, 2023). "Bycontrast, the corn oil intervention did not recover the neuroinflammation.The GFAP expression has been demonstrated as a reliable marker presentingthe astrocytes’ accumulation in aging individuals, but in patients with depression, it was stillinconsistent." (PMID 37769277, 2023). "However, we do find that lower GFAP is related to more severe psychopathology, including PTSD, depression, stress, neurobehavioral symptoms, and pain." (PMID 35217643, 2022). "The correlation between apathy/depression and GFAP was not in fluenced by other factors such as age or HIV suppression status." (PMID 37205974, 2022). "Although apathy is a particularly prominent and disabling component of depression in PWH and HIV causes astrocyte activation, no previous study has evaluated CSF GFAP levels in PWH in the setting of depression and apathy." (PMID 37205974, 2022). "Recently, the study demonstrated that 6 weeks of running exercise significantly increased the number of GFAP+ cells and the density of BrdU+/GFAP+ cells in the hippocampal CA1 region and DG in a rat model of depression, suggesting the role of exercise to promote the generation of new astrocytes." (PMID 34207393, 2021). "Downregulation of miR-383 significantly inhibited the apoptosis and inflammatory response of hippocampal neurons, and increased the expression levels of GFAP, BDNF and CREB which were impacted in depression, as well as neurotransmitters, then attenuated neural injury in rats induced by CUMS." (PMID 33927285, 2021). "This was for a certain extent is in agreement with who reported that fluoxetine could prevent GFAP reduction and glial atrophy and restore the integrity of astrocytes in CUMS-induced animal model of depression." (PMID 33061923, 2020). "In summary, this investigation suggests that GFAP-positive astrocyte-specific deletion of GLT1 decreased anxiety- and depression-like behaviors, which may provide novel insights toward the underlying mechanisms of mood related psychiatric disorders." (PMID 32390810, 2020). "Additionally, the expression levels of glial fibrillary acidic protein (GFAP), a marker of astrocytes, is found to be decreased in patients suffering with depression." (PMID 31312123, 2019). "To summarize, specific GFAP dysregulation in the ACC and/or DLPFC are associated with aged and non-suicidal depression." (PMID 31798416, 2019). "It is well reported that human postmortem tissue in major depressive disorders (MDD) have shown alterations in the expression of mRNA and protein for astrocyte markers such as GFAP, Cx40, Cx43, AQP4, S100β and glutamatergic markers including GLT-1, GLAST, and GS." (PMID 32341961, 2018).
depression (continued). "Given that both males and females showed similar reductions in saccharin intake, it is unlikely that the differential sex impairments in GFAP, GLT-1, and glutamate accumulation or glutamine release are simply due to the differential aggression used to produce the depression models." (PMID 28018190, 2016). "One possible hypothesis for our findings may be that depression is associated with lower baseline (i.e. pre-injury) GFAP concentrations, resulting in lower post-injury GFAP levels after TBI in comparison to TBI participants without pre-injury depression." (PMID 40190352, 2025). "Interestingly, the expression of astrogliosis markers presented a more complex pattern with GFAP and aquaporin-4 (AQP4) levels being lower in MTLE patients with mental disorders and depression specifically, whereas Metallothioneins I/II (MT-I/II) levels being higher." (PMID 40177583, 2025). "hypocretin‐1 model, and hippocampal GFAP‐HCRTR1‐KD model, which demonstrated HCRTR1 affects the reduction of lactate release from hippocampal astrocytes and impairs synaptic plasticity and neurogenesis, thus playing an important role in cognitive dysfunction in depression." (PMID 39119889, 2024). "A study reported that EA therapy could reduce depression manifestations in CUMS rats, and the concentration of GFAP protein in their brains as well as the mean optical density of GFAP-immunoreactive astrocytes (GFAP-ir astrocytes) could be increased (n = 20, P < 0.05)." (PMID 38536776, 2024). "Interestingly, ZW inhibited diabetes-induced anxiety and depression by minimizing the neuroinflammatory response by decreasing NfκB, IL-1β, and IL6 mRNA levels and the number of TNF-α- and GFAP-immunostained neurons and serum level of TNF-α and CRP because of its antioxidant power." (PMID 38105928, 2023). "On the other hand, microglia from GFAP-IFN mice were hypertrophied, had longer processes and were hyper-ramified, comparable to microglia in the brain of mice reported during aging, chronic stress, IFN-α-induced depression and following chronic, CNS-targeted production of IFN-β." (PMID 35429976, 2022). "Besides, XYS may be critical to the treatment of depression by intervention the HPA axis, GFAP and Glu-NMDA receptor." (PMID 33192662, 2020). "Changes in the hippocampus GFAP and Glu-NMDA receptor may be an essential mechanism of depression." (PMID 33192662, 2020). "The expression levels of astrocyte markers (glial fibrillary acidic protein (GFAP), synemin-α, synemin-β, vimentin, nestin) in isolated gray matter from postmortem ACC and DLPFC were determined to investigate the possible involvement of astrocytes in depression." (PMID 31798416, 2019). "GFAP concentration was lower in those with probable anxiety (GAD-7), likely depression (PHQ-9), and probable PTSD (PCL-5), but not significant after adjusting for multiple comparisons (eTables 12–14)." (PMID 39652812, 2025). "We did not investigate the temporal expression of GFAP in our samples, but we found a report of gradual reduction in GFAP expression following IGF-1 treatment in a rodent model of depression." (PMID 27272754, 2016). "In the prefrontal cortex of human subjects with depression, the coverage of vessels by the aquaporin 4 (AQP-4)-immunoreactive endfeet of astrocytes is significantly reduced, even if the extent of those feet is not changed when labeled for the cytoskeletal protein GFAP." (PMID 35530179, 2022).
diabetes (139 papers, 2010 to 2026). "Our result seems to be comparable with an increasing number of studies that show that diabetes is associated with reactive Müller cell gliosis, which is characterized by increased levels of GFAP." (PMID 35163285, 2022). "MGC is the main source of VEGF in the retina, and the increase in VEGF triggered by diabetes is associated with upregulation of GFAP, a signal of gliosis." (PMID 35453302, 2022). "Two studies demonstrated that minocycline treatment prevented an increase in acetylation of histones at the promoters of GFAP and cytokine genes caused by culturing Müller glia cells under diabetes-like (high glucose) conditions." (PMID 34446062, 2021). "In SE-housed animals, experimental diabetes induced a slight increase in retinal GFAP- immunoreactivity associated with activated Müller cells, whereas EE housing prevented the increase in this parameter." (PMID 25004165, 2014). "In the human retina during early diabetes, retinal Müller cells change from quiescent to an injury-associated phenotype and express high levels of GFAP." (PMID 20652025, 2010). "Reduced serum GFAP levels may be associated with reduced markers of small nerve fiber damage obtained from quantitative sensory testing in people with diabetes." (PMID 40192786, 2025). "Additionally, recent studies have indicated a significant association between GFAP levels and diabetes, demonstrating that GFAP levels are elevated in diabetic animals, particularly in relation to neuroinflammatory processes." (PMID 39594187, 2024). "Furthermore, double-immunofluorescence labeling revealed that diabetes or Drp1 loss led to an increased intensity in both the ionized calcium-binding adaptor molecule (Iba-1) and glial fibrillary acidic protein (GFAP), in the hippocampus." (PMID 33953167, 2021). "Diabetes is associated with RMC activation that is characterized by GFAP increase in the cells." (PMID 34750361, 2021). "It has been documented that insulin‐treated rats had increased astrocytic GFAP as compared to diabetic rats; therefore, insulin is of great importance in improving the function of astrocytes, the dysfunction of which is implicated in the CNS complications of diabetes." (PMID 38639646, 2024). "Also, reduced GFAP has been linked to certain metabolic conditions such as Diabetes." (PMID 36818564, 2023). "Recently a case-control study based on data from the EUROCONDOR trial showed that GFAP-levels were higher at baseline in diabetes patients developing retinal neurodysfunction (as measured by multifocal electroretinography) two years later." (PMID 40141267, 2025). "In a diabetes model induced by STZ, the cerebellum of 8 week diabetic mice presented elevated immunostaining for GFAP associated with increased oxidative stress, which was characterized as glial reactivity." (PMID 40429951, 2025). "Altogether, these lines of evidence appear in favor of our observation of reduced serum GFAP in persons with diabetes complicated by DPN." (PMID 40192786, 2025). "Multivariable linear regression analyses including age, BMI, mGFR, U-ACR, B-hemoglobin, S-TnT, gender, diabetes, and smoking as independent variables were performed to predict log-transformed plasma concentrations of NfL, p-Tau231 and GFAP." (PMID 40346521, 2025). "GFAP, hsa-miR-15b-5p, and rno-miR-15b-5p all have binding sites, and miR-15b-5p is downregulated in diabetes." (PMID 38967699, 2024). "Diabetes significantly elevated GFAP+ immunoreactivity in FKNKO mice (33.82 ± 4.54), which was decreased with rAAV–sFKN (23.51 ± 3.02, Student’s t test p < 0.01) but not rAAV–mFKN (30.20 ± 3.36)." (PMID 38311721, 2024). "After 9 mo of diabetes induction, immunohistochemistry of central retinal tissue showed that the number of GFAP fibers increased significantly in STZ diabetic retinas, when compared to nondiabetic animals." (PMID 39348530, 2024).
diabetes (continued). "In Cx3cr1–/– mice, whose microglia showed enhanced inflammatory responses, we found evidence of IL-1β expression by GFAP+ astrocytes with a corresponding decrease in their overall GFAP immunoreactivity area at 20 weeks of diabetes." (PMID 38785974, 2024). "These explanations suggest a link between reductions in GFAP and diabetes‐induced CNS complications." (PMID 38639646, 2024). "Our findings demonstrated that GFAP expression in Müller cells increases as diabetes progresses and provided the first evidence that PRDX4 suppressed reactive gliosis of Müller cells during DR." (PMID 39706273, 2024). "In response to diabetes, we observed an increase in GFAP+ immunoreactivity in the PBS-treated diabetic mice (20.34 ± 2.81) compared to their ND counterparts (7.81 ± 2.16, one-way ANOVA p < 0.01)." (PMID 38339005, 2024). "They increase expression of the intermediate filament glial fibrillary acidic protein in both human and rodent models of diabetes, indicating that gliosis of these cells occurs from an early stage of diabetes." (PMID 36349522, 2023). "Müller cells become activated in diabetes as evidenced by increased expression of glial fibrillary acidic protein (GFAP), a common marker of reactive gliosis." (PMID 35907890, 2022). "GFAP expression was elevated in diabetic retinas at 4 and 12 weeks after diabetes onset (both p < 0.001)." (PMID 35334819, 2022). "In a previous study, SR141716 was shown to block diabetes-induced activation of Müller cells (GFAP IR) and NFκB, localized in the vascular layers of the retina, in a mouse STZ model of DR." (PMID 36613692, 2022). "Nicotinamide treatment significantly attenuated GFAP immunofluorescence staining at 4 and 12 weeks after induction of diabetes (Both p < 0.001)." (PMID 35334819, 2022). "In accordance with these findings, we show that diabetes increased the number of Iba1 + cells and GFAP expression in Müller cells in the two-week model of DR." (PMID 36613692, 2022). "Upregulation of GFAP occurs in response to hyperglycemia; however, this is not an immediate response, but one that increases with time and duration of diabetes." (PMID 38983568, 2022). "Increase in GFAP labelling in MGC, a hallmark of glia stress and reactivity, is detected in diabetes induction models." (PMID 35453302, 2022). "The elevated expression of glial fibrillary acidic protein (GFAP) induced by diabetes was attenuated by nicotinamide treatment." (PMID 35334819, 2022). "GFAP was the only diabetes gene tested that was significantly decreased in the DMT1-NOD mice and mildly increased in the DMT2 db/db mice." (PMID 36613769, 2022). "For example, in the early stage of diabetes, the glial fibrillary acidic protein (GFAP) expression is increased in Müller cells and decreased in astrocytes." (PMID 35010703, 2021). "High levels of hippocampal GFAP, were found in diabetic animals following a running exercise using a treadmill apparatus, suggesting that physical training prevents and/or reverts diabetes-induced astrocytic GFAP reduction in the hippocampus." (PMID 34207393, 2021). "GFAP is typically produced by astrocytes in healthy conditions and by other retinal cells, such as activated Müller cells, in diabetes." (PMID 34216255, 2021). "Glutamine synthase (GS) levels increased in the retina in our experiments during diabetes, while levels of glial fibrillary acidic protein (GFAP) also followed this trend." (PMID 34943979, 2021). "Diabetes significantly upregulated the level of GFAP, concomitant with exacerbated reactive gliosis." (PMID 33089077, 2020). "It is known that Müller cells become activated in the retina during diabetes, and the expression of the glial fibrillary acidic protein (GFAP) is increased in the Müller cells and is a characteristic feature of the diabetic retina." (PMID 33233661, 2020).
diabetes (continued). "Our results are consistent with previous data, suggesting that GFAP and VEGF expression was increased in the whole retina of diabetic rats, Thus, the reactive gliosis caused by diabetes, is enhanced." (PMID 31938037, 2020). "This change precedes the increase in GFAP expression that is up-regulated after a few weeks of experimental diabetes onset." (PMID 30401898, 2019). "Lisosan G has been reported to block increases in GFAP mRNA expression, indicating reactive gliosis, induced by diabetes in the retinas of STZ rats." (PMID 30987058, 2019). "HIF-1alpha, VEGF and GFAP started to increase at 1 month and vimentin at 4 months after diabetes onset." (PMID 30401898, 2019). "Curcumin has also been observed to reverse the diabetes-induced upregulation of retinal GFAP in Müller cells of STZ rats." (PMID 30987058, 2019). "Diabetes induced glial activation in the retina, characterized by increased GFAP expression in Müller cells, has also been found to be inhibited by green tea or by epicatechin." (PMID 30987058, 2019). "The immunofluorescence result showed that both GFAP and vimentin were co-localised with GS in 4-month diabetic rat retinas, indicating the activation of Müller cells in diabetes." (PMID 30401898, 2019). "This compound has also been observed to inhibit the diabetes-induced over-expression of GFAP and of the pro-inflammatory cytokines TNFα and IL-1β in retinas of diabetic rats." (PMID 30987058, 2019). "In diabetes, the Müller cells are dysfunctional due to an increased synthesis of glutamate, increase in glial fibrillary acidic protein, and Müller cell swelling due to downregulation of the Kir4.1 channels." (PMID 29474462, 2018). "Müller cells and astrocytes undergo activation in diabetes, and GFAP expression in Müller cells is widely considered to be a sensitive marker of retinal stress." (PMID 30574423, 2018). "It is already known that diabetes induces abnormalities in retinal Müller cells, including increased GFAP expression, reduced glutamine synthetase and decreased glutamate transporter activity." (PMID 30475883, 2018). "In diabetes, many of these important functions become disturbed and the cells assume a reactive phenotype characterised by the upregulation of glial fibrillary acidic protein (GFAP) and the production of inflammatory chemokines and cytokines." (PMID 30112688, 2018). "Retinal neurons are known to be injured during the early stages of diabetes, and Müller cells react to retinal injury (gliosis), as indicated by radial GFAP expression." (PMID 28492550, 2017). "Increased levels of GFAP have been reported within 6–8 weeks of diabetes induction in animal models." (PMID 28238189, 2017). "The treatment with minocycline significantly reduced the diabetes-induced up-regulation of GFAP both by western blot analysis and immuno-histochemical staining, indicating that minocycline suppressed the diabetes-induced glial activation." (PMID 28338045, 2017). "Müller cell gliosis, evidenced by an upregulation of GFAP, was apparent at 6 weeks of diabetes in the central and mid retina, and at 12 weeks in the peripheral retina." (PMID 26852722, 2016). "As shown herein, EE housing prevented the increase in GFAP immunoreactivity in the distal portion of the ON at early stages of experimental diabetes." (PMID 26312758, 2015). "Exogenous insulin treatment can prevent the diabetes induced changes in astrocyte glutamate uptake and GFAP expression in the brain." (PMID 25759824, 2015). "Retinal immunoreactivity for GFAP and vimentin were analyzed at 6 weeks of diabetes in animals housed in SE or EE." (PMID 25004165, 2014). "Staining of GFAP in the spinal cord was barely noticeable in rats receiving vehicle, while significantly increased in the dorsal horn on day 27 after diabetes induction (P < 0.001)." (PMID 25089076, 2014).